LRIG1 (leucine rich repeats and immunoglobulin like domains 1)
Diseases named in the same sentence as LRIG1 in open-access papers (continued):
Sharing a sentence is not in itself a finding about the gene and the disease.
tumor (continued). "Limiting-dilution tumor regeneration assays in LAPC4 and LAPC9 AD models revealed tumor-promoting effects upon LRIG1 knockdown, as evidenced by increased tumor incidence." (PMID 31792211, 2019). "Control Lrig1-CreERT2 tissue showed robust Oct1 expression in both tumor and gross uninvolved (GU) areas." (PMID 31059499, 2019). "Preceding experiments demonstrate tumor-suppressive functions of LRIG1 in both human xenograft and murine genetic PCa models." (PMID 31792211, 2019). "The positive correlation between LRIG1 mRNA levels and better PCa patient OS suggests a potential tumor-suppressive function of LRIG1 in PCa." (PMID 31792211, 2019). "LRIG1 participates in the aggressive progression of several tumours, in which its expression is frequently decreased." (PMID 31703415, 2019). "Whereas tumor‐suppressive functions of LRIG1 and LRIG3 have been reported in malignant glioma, LRIG2 seems to act more as an oncoprotein." (PMID 31580518, 2019). "Overexpression of LRIG1 in LNCaP AI cells exhibited inhibitory effects on both tumor incidence and growth whereas knocking down endogenous LRIG1 in LAPC9 AI cells promoted both tumor regeneration and growth in a limiting-dilution tumor assay." (PMID 31792211, 2019). "Collectively, our study indicates that LRIG1 represents a pleiotropic AR-regulated feedback tumor suppressor that functions to restrict oncogenic signaling from AR, Myc, ERBBs, and, likely, other oncogenic drivers." (PMID 31792211, 2019). "The striking finding that knocking down endogenous LRIG1 in 3 AR+ PCa models promotes tumor regeneration/growth suggests that LRIG1 intrinsically represses tumorigenicity of AR+ PCa cells." (PMID 31792211, 2019). "Leucine-rich repeats and immunoglobulin-like domains 1 (LRIG1) is a tumor suppressor and a negative regulator of several receptor tyrosine kinases." (PMID 29317492, 2018). "The molecular mechanisms by which LRIG1 mediates its tumor suppressor effects and regulates receptor tyrosine kinases remain incompletely understood." (PMID 29317492, 2018). "The overall tumor incidence was similar among the genotypes; however, the incidence of high-grade tumors was significantly higher in the Lrig1-heterozygous mice than that in the wild-type mice (19.6 vs. 1.6%, respectively; Pearson’s test, p = 0.002)." (PMID 29391393, 2018). "Here, we showed that Lrig1 was a haploinsufficient tumor suppressor of PDGFB-induced experimental diffuse glioma in mice." (PMID 29391393, 2018). "To test the impact of si-LRIG1 on tumor cell apoptosis and proliferation, we stained the tumor sections with H&E, TUNEL and Ki67." (PMID 30081934, 2018). "Next, we examined the mRNA level of LRIG1 and miR-301b in tumor and normal skin samples, and the results showed that mRNA level of LRIG1 was lower and mRNA level of miR-301b higher in tumor tissue compared to that of in normal skin tissue." (PMID 30081934, 2018). "Intriguingly, the different tumours induced by stabilizing β-catenin in Lgr5+, Lgr6+, and Lrig1+ epithelial cells exhibit both similarities and differences in stromal composition." (PMID 29807713, 2018). "To gain further insight into the correlation between LRIG1 and miR-301b clinically, we used dataset GSE46517 and GSE15606 from GEO database to measure the expression level of LRIG1 in primary tumor tissue and normal skin tissue." (PMID 30081934, 2018). "Administration of the shed portion of LRIG1 to cells inhibited EGF signaling suggesting that processing is necessary for this substrate to act as a tumor suppressor." (PMID 29230082, 2017). "LRIG1 has been proposed to function as a tumour suppressor through negative regulation of oncogenic receptor tyrosine kinases, such as members of the ERBB family, MET and RET receptors, and PDGFRA." (PMID 28841699, 2017). "The leucine-rich repeats and immunoglobuline-like domains (LRIG)-1 protein functions as a tumour suppressor, but less is known about the functions of LRIG2 and LRIG3." (PMID 28841699, 2017).
tumor (continued). "As the tumor lesions progressed in the back skin of 4-OHT-treated Lrig1 KI/R26R-tdTomato/Ctnnb1lox(ex3)/+ mice, collagen was comprehensively remodeled and the dermis was almost entirely filled with compact immature collagen characteristic of tumor stroma." (PMID 26771241, 2016). "Their RNASeq data indicated that MSI‐2 acts as a pleiotropic inhibitor of known intestinal tumor suppressors, including Lrig1, Bmpr1a, Cdkn1a, and Pten." (PMID 26775684, 2016). "The differentiation status, tumor stage, and LRIG1 expression levels were predictors of OS in the 2 cohorts as demonstrated by the univariate analysis." (PMID 26632716, 2015). "In contrast, expression of Plet1 and Lrig1, markers for progenitors and SCs of the upper IR and JZ, respectively, were strongly expressed within SC-driven tumours." (PMID 25608467, 2015). "Robust expression of Lrig1 and Plet1 was also detected by immunofluorescence staining in K15ΔNLef1 tumours." (PMID 25608467, 2015). "The LRIG1 is a negative regulator of growth factor signaling functioning as a tumor suppressor in mice models whereas the function of LRIG2 and LRIG3 are less well defined." (PMID 25653716, 2015). "In contrast, aggressive sebaceous tumours of K15ΔNLef1 mice showed Lrig1+ cells distributed throughout the tumour mass." (PMID 25608467, 2015). "In this study, according to tumor differentiation status and stages, a significant downregulation of LRIG1 mRNA was observed in NSCLC tissues." (PMID 26632716, 2015). "The correlation between LRIG1 mRNA levels and clinical characteristics in the cancer tissues (pathological type, differentiation status, and tumor staging) was further analyzed." (PMID 26632716, 2015). "The results demonstrated that differentiation status, tumor staging, and LRIG1 expression levels were all independent prognostic factors for NSCLC." (PMID 26632716, 2015). "The leucine-rich repeats and immunoglobulin-like domains (LRIG)-1 is a tumor suppressor gene that belongs to the LRIG family." (PMID 26632716, 2015). "Malignant tissue with proliferative potential presented EGFR overexpression and inverse downregulation of LRIG1, consistent with LRIG1 being a suppressor of neoplastic transformation by counteracting the tumor growth property of EGFR." (PMID 24709893, 2014). "LRIG1, which has been extensively studied, is proved to be a tumor suppressor and the soluble LRIG1 ectodomain has also been found to act as a negative regulator of tumor growth." (PMID 25353163, 2014). "Accumulating evidence indicates that LRIG1 functions as a tumor suppressor in humans by negatively regulating tyrosine kinase receptors of the EGFR family." (PMID 25353163, 2014). "These novel findings lend support to the suggestion that LRIG1 acts as a tumor suppressor and negative regulator of EGFR." (PMID 24709893, 2014). "To date, the tumor suppressing function of LRIG1 has mainly been attributed to its inhibitory effect on EGFR signaling." (PMID 24709893, 2014). "In this present study, the possible function of LRIG1 on tumor progression was investigated via immunofluorescence analysis in human OSSN." (PMID 24709893, 2014). "Consistent with its proposed role as a tumor suppressor gene, Lrig1 can control the activity of several receptor tyrosine kinases (rTKs) with important effects on cell proliferation and survival." (PMID 24086156, 2013). "Of note, however, LRIG1 expression is up-regulated in some tumours, suggesting that the gene functions as a tumour promoter under certain circumstances." (PMID 19779621, 2009). "In well and moderately differentiated tumours Lrig1 was detected in the suprabasal layers, correlating with areas that were Ki67 negative and consistent with Lrig1 expression in normal oral mucosa (data not shown)." (PMID 18657901, 2008). "In 4/5 poorly differentiated tumours Lrig1 was either undetectable (−) or expressed in only occasional cells (−/+ or +)." (PMID 18657901, 2008).
tumor (continued). "We confirmed our scoring for Lrig1 expression on one sample of normal skin and five tumours, picked at random using an Applied Imaging Ariol® system." (PMID 18657901, 2008). "Lrig1 was detected in well and moderately differentiated tumours but was markedly reduced in poorly differentiated tumours." (PMID 18657901, 2008). "While Lrig1 was consistently downregulated in unfractionated SCC lines and primary tumours, the levels of Lrig1 in the stem cell-enriched fractions were remarkably similar to normal oral and epidermal stem cells." (PMID 18657901, 2008). "Four tumours with increased LRIG1 copy number were analysed by RT-PCR for EGFR/ERBB1, and all four showed significantly lower expression of EGFR/ERBB1 and three showed significantly higher expression of ERBB2 than their matched normal controls." (PMID 16168117, 2005). "LRIG1 mRNA was significantly overexpressed in two of the seven tumours and significantly underexpressed in two of the seven tumours." (PMID 16168117, 2005). "Normal signal pattern corresponding to two LRIG1 copies per nucleus was detected in the remaining five tumours." (PMID 16168117, 2005). "Intriguingly, EGFR/ERBB1 mRNA was significantly underexpressed in all of the four tumours analysed with increased LRIG1 copy number." (PMID 16168117, 2005). "An increased copy number of LRIG1 was seen in more than 20% of the nuclei in 7 of the 19 tumours (in most cells three to five signals)." (PMID 16168117, 2005). "Genetic studies have implicated a tumour suppressor gene on chromosome arm 3p and we have proposed LRIG1 at 3p14 as a candidate tumour suppressor." (PMID 16168117, 2005). "Normal signal pattern corresponding to two copies per nucleus was detected in 11 of the 19 tumours, and 1 tumour demonstrated decreased copy number of LRIG1." (PMID 16168117, 2005). "In all four tumours with increased LRIG1 copy number, expression of LRIG1 protein was higher than in the matched non-neoplastic breast tissue, as assessed by western blot analysis." (PMID 16168117, 2005). "The LRIG1 gene showed increased copy number in 11 out of 28 tumours (39%) and only one tumour showed a deletion at this locus." (PMID 16168117, 2005). "The three tumours with increased LRIG1 copy number (FISH analysis) that were able to be analysed by RT-PCR for LRIG1 showed significant overexpression of LRIG1 mRNA in two cases." (PMID 16168117, 2005). "The ratio between EGFR and LRIG1 was more than 2.5-fold higher in the eight tumours compared with matched uninvolved kidney cortex and was at least two-fold higher than the mean normal ratio in 21 of 31 samples analysed." (PMID 14520461, 2003). "The observed downregulation of LRIG1 and increased EGFR/LRIG1 ratios are consistent with LRIG1 being a suppressor of oncogenesis in RCC by counteracting the tumour-promoting properties of EGFR." (PMID 14520461, 2003). "In tumours, the intensity of LRIG1 staining was generally less pronounced than in the kidney cortex tissue." (PMID 14520461, 2003). "The increased EGFR/LRIG1 ratio found in RCC lends support to the suggestion that LRIG1 functions as a tumour suppressor and inhibitor of EGFR in humans." (PMID 14520461, 2003). "This novel finding in a human tumour specimen lends support to the suggestion that LRIG1 acts as a tumour suppressor and negative regulator of EGFR." (PMID 14520461, 2003). "LRIG1 expression appeared downregulated in the majority of tumours and was decreased in six of eight tumours compared with kidney cortex tissue from the same patient." (PMID 14520461, 2003). "The EGFR/LRIG1 ratio was increased at least 2.5-fold in all tumours matched with the corresponding kidney cortex." (PMID 14520461, 2003). "Conventional RCC obviously displayed lower expressions of LRIG1 than the kidney cortex, six of eight matched tumour samples had decreased expression and one was unchanged compared to kidney cortex tissue." (PMID 14520461, 2003).
tumor (continued). "KVA12123, a next-generation IgG1, binds VISTA across both pH environments, blocks interactions with multiple ligands (PSGL-1, VSIG3, VSIG8, LRIG1), and demonstrates strong receptor occupancy and anti-tumor efficacy with minimized FcγR engagement in Phase I/II studies." (PMID 41486149, 2026). "Thus, our finding of higher LRIG1 in secondary GBMs, which have a better prognosis, matches previous assumptions of LRIG1 being a tumor suppressor." (PMID 41201961, 2025). "As a tumour suppressor, downregulating LRIG1 also led to a more aggressive tumour type." (PMID 40869298, 2025). "LRIG3 seems to have functions similar to LRIG1, showing a more tumor-suppressive potential." (PMID 41201961, 2025). "LRIG1 is involved in modulation of signaling from growth factors and acts as a tumor suppressor." (PMID 39640846, 2024). "It occurs in the same cell (cis) and in different cells (trans), and VISTA may be involved in the inhibitory signaling exerted by LRIG1 to drive the quiescence of tumor-responsive CTLs." (PMID 39742253, 2024). "Tamoxifen-induced Lrig1-CreERT2/+ Apcfl/+ Selenop+/+, Selenop+/–, and Selenop–/– cohorts (hereafter referred to as ApcΔIE/+ Selenop+/+, Selenop+/–, and Selenop–/– mice) were monitored for tumor formation via colonoscopy and euthanized after 100 days." (PMID 37166989, 2023). "This suggests that Lrig1 overexpression reduces tumour progression in vivo." (PMID 36420140, 2022). "We have shown that LRIG1 exerts a tumour suppressive role in LUSC development." (PMID 34385275, 2022). "Lrig1 may therefore be a useful cell surface marker to track quiescent and proliferative tumour compartments and their signalling responsiveness." (PMID 36420140, 2022). "Dysregulation of LRIG1 is seen across different tumour types." (PMID 34385275, 2022). "To analyse the effect of Lrig1 loss on the tumour-initiating capacity of GSCs we employed two approaches: first, ex vivo GSC transplantation of Lrig1 WT or Lrig1 KO GSCs into organotypic slice cultures; and second, in vivo transplantation into immunocompromised (NSG) mice." (PMID 36420140, 2022). "However, 12 weeks after tumor initiation, we noticed multiple black dots exclusively on the back skin of LRIG1‐TG animals, resembling melanocytic nevi." (PMID 33786987, 2021). "Notably, LRIG1‐TG mice developed melanocytic tumors, which were visible 12 weeks after tumor initiation." (PMID 33786987, 2021). "Therefore, the main goal of the present study was to compare and analyze the expression levels of the LRIG1 gene in samples of tumor and normal colorectal tissues of CRC patients by quantitative real-time RT-PCR and immunohistochemical (IHC) techniques." (PMID 33461538, 2021). "LRIG1 is highly related to tumour development in multiple cancers." (PMID 34257270, 2021). "Moreover, LRIG1 restricts estrogen-driven tumor cell growth, suggesting that it can suppress ERα-positive tumors." (PMID 34359928, 2021). "Although the overexpression of LRIG1 in cancer cells may effectively suppress the growth of the tumor, in normal tissues, the accumulation of LRIG1 might delay tissue repair and aggravate the illness." (PMID 34576152, 2021). "Taken together, while LRIG1 might be a promising target for tumor therapy in the skin by influencing the ERBB signaling network, the molecular function and the underlying mechanisms are largely unknown." (PMID 33786987, 2021). "In the present ddPCR study, we used a reference gene on another chromosome to normalize the LRIG1 copy number according to the cell number and tumor ploidy, whereas in the previous study, the LRIG1 FISH signals were only normalized to the number of cells, i.e., the number of cell nuclei." (PMID 32448168, 2020). "Higher expression of LRIG1 was a good prognostic biomarker associated with the prolonged survival outcomes in the ACC, LGG and LUAD cancer patients after adjusting for the abundances of tumor infiltrating immune cells." (PMID 31358815, 2019).
tumor (continued). "Of significance, ablation of Lrig1 results in duodenal adenomas and other GI tumors associated with increased expression of ERBB1-3 and some ligands, providing genetic evidence that LRIG1 functions as a tumor suppressor." (PMID 31792211, 2019). "LRIG1 has been reported to be a tumor suppressor in gastrointestinal tract and epidermis." (PMID 31792211, 2019). "We further tested the tumor-suppressive functions of LRIG1 in genetic mouse models." (PMID 31792211, 2019). "However, the low-grade Oct1fl/fl;Lrig1-CreERT2 tumors that did occur showed a higher proportion of tumor tissue that retained Oct1 expression compared to GU tissue in the same section." (PMID 31059499, 2019). "Interestingly, however, the LRIG1 mRNA levels showed a decreasing trend (P = 0.00547, Jonckheere-Terpstra test) with increasing tumor grade, i.e., from GS (Gleason Score) 6 to GS9 tumors." (PMID 31792211, 2019). "Indeed, in accordance with the in vitro data, LRIG1 displayed a decreased expression in patient derived xenograft that proved to be resistant to EGFR blockade (tumor volume increase of at least 35% compared to the initial pre-treatment volume)." (PMID 31052457, 2019). "Shortly after LRIG1 was cloned, it was hypothesized to function as a potential tumor suppressor gene because the genomic region that harbors the gene, 3p14.3, is frequently deleted in human cancers." (PMID 31792211, 2019). "Similarly, ~2 weeks following establishing PC3 xenografts, LRIG1 induction inhibited both tumor growth rate and weights." (PMID 31792211, 2019). "Subsequently, we determined how LRIG1 overexpression might influence tumor regeneration and growth in PCa cells that expressed little endogenous LRIG1." (PMID 31792211, 2019). "Correlation of LRIG1 expression with better patient survival and tumor-suppressive functions of LRIG1 suggest that this molecule may be of diagnostic and prognostic values in PCa." (PMID 31792211, 2019). "Because ablating one copy of Lrig1 resulted in a decrease of Lrig1 expression and an increase in the tumor grade (grade IV vs. grade II–III), we surmised that there exists a relationship between the reduced expression of Lrig1 and the increased malignancy of tumors." (PMID 29391393, 2018). "Many of the described LRIG1 interactors were not previously anticipated to be regulators of LRIG1 function and therefore will provide novel leads in the quest to understand the molecular function of LRIG1 and its association with tumor suppression." (PMID 29317492, 2018). "Furthermore, multivariate Cox proportional hazards regression analysis indicated that the differentiation status, tumor stage, and LRIG1 expression levels were independent prognostic factors for NSCLC in both cohorts." (PMID 26632716, 2015). "Notably, a significant correlation was observed between the LRIG1 expression and the tumor stage (P = 0.003)." (PMID 26632716, 2015). "In contrast, a pool of more lineage-restricted SCs, for example, Lrig1+ tumour cells, is enriched and therefore, could drive tumour growth outside the normal SC niche." (PMID 25608467, 2015). "To confirm the significant value of LRIG1 for predicting the prognosis in NSCLC, we have analyzed the correlation between sex, age, pathological type, differentiation status, tumor staging, smoking history and LRIG1 expression levels with OS, and assessed the prognostic efficacy of LRIG1." (PMID 26632716, 2015). "The human LRIG1 gene is located at chromosome 3p14.3, which is a region frequently deleted in human cancers, suggesting that LRIG1 might be a tumor suppressor gene." (PMID 24709893, 2014). "Increasing evidence indicates that, in certain cancer types, LRIG1 is a tumor suppressor." (PMID 25013483, 2014). "Lrig1 is a tumor suppressor gene required for normal EGF signaling." (PMID 24086156, 2013). "Moreover, LRIG1, a gene coding for a protein with recognized tumor suppressing properties, was upregulated by KGF in SCC cells." (PMID 22427941, 2012).